PTX3 (pentraxin 3)
Diseases named in the same sentence as PTX3 in open-access papers (continued):
Sharing a sentence is not in itself a finding about the gene and the disease.
skin infection (1 paper, 2026). An inflammatory process affecting the skin, caused by bacteria, viruses, parasites, or fungi. "This review systematically examines the diagnostic value and immunomodulatory role of PTX3 across a spectrum of infectious diseases, including those affecting the respiratory, cardiovascular, digestive, urinary, and nervous systems, as well as orthopedic and skin infections." (PMID 41800408, 2026).
Sleep apnea (1 paper, 2016). An intermittent cessation of airflow at the mouth and nose during sleep is known as sleep apnea. "Furthermore, other kinds of inflammatory conditions, such as sleep apnea and cardiac valvular disease, have shown the significant correlations with PTX3, and we could not exclude all the conditions, which might affect our result." (PMID 27559483, 2016).
Splenomegaly (1 paper, 2020). Abnormal increased size of the spleen. "We also measured plasma levels of GM-CSF, G-CSF, HMGB-1 and pentraxin 3, because they have all been linked to splenomegaly." (PMID 32824440, 2020).
sporotrichosis (1 paper, 2021). The commonest and least serious of the deep mycoses, characterized by nodular lesions of the cutaneous and subcutaneous tissues. "The mechanisms involving PTX3 and complement factors related to the physiopathology of sporotrichosis need to be investigated further." (PMID 34867977, 2021).
Streptococcus pneumonia (1 paper, 2022). "It was also shown that in Ptx3−/− mice infected with Streptococcus pneumonia (SP) there was impaired production of SP-specific IgM and IgG as well as class switching from IgM to IgG." (PMID 35956001, 2022).
synovitis (1 paper, 2022). Inflammation of a synovial membrane. "Taken together, these results suggest a role for PTX3 in the reprogramming of macrophages and OA synovitis." (PMID 35739102, 2022).
thrombotic disease (1 paper, 2014). The formation of a blood clot in the lumen of a vessel or heart chamber; causes include coagulation disorders and vascular endothelial injury. "Recently, some report suggested a crucial protective role of PTX3 in thrombotic diseases." (PMID 25587447, 2014).
uremia (1 paper, 2013). A clinical syndrome associated with the retention of renal waste products or uremic toxins in the blood. "Furthermore, we cannot discard the possibility that normalization of circulating PTX3 after transplantation may, in addition to reversal of uremia, be secondary to immunosuppressive therapy." (PMID 23658833, 2013).
urothelial carcinoma (1 paper, 2024). A malignant neoplasm derived from the transitional epithelium of the urinary tract (urinary bladder, ureter, urethra, or renal pelvis). "However, BC patients with histological elements of sarcomatoid or squamosal cell differentiation had higher median levels of PTX3 (p = 0.053) compared to patients diagnosed with pure urothelial carcinoma tumours." (PMID 38542446, 2024).
variceal (1 paper, 2020). "Related to the function of PTX3 in coagulation, tissue injury was associated with higher local and systemic PTX3 in a skin-wounding model, and similar mechanisms may account for higher PTX3 in patients with variceal bleeding." (PMID 32078718, 2020).
viral meningitis (1 paper, 2023). Inflammation of the membranes surrounding the brain and spinal cord due to a viral infection. "CSF PTX3 in patients with viral meningitis was significantly higher than among control group patients irrespectively of the inclusion of viral meningitis with an unknown pathogen (p = 0.0001)." (PMID 36862691, 2023).
viral myocarditis (1 paper, 2018). Myocarditis that is caused by an infection with a viral agent. "During viral myocarditis, PTX3 is produced mainly by monocytes and macrophages." (PMID 30546359, 2018).
visceral leishmaniasis (1 paper, 2025). A severe form of leishmaniasis characterized by irregular bouts of fever, substantial weight loss, swelling of the spleen and liver, and anemia (which may be serious). "Importantly, to our knowledge, this is the first study to assess plasma PTX3 concentrations together with PTX3 gene polymorphisms in human visceral leishmaniasis." (PMID 41471254, 2025). "PTX3 concentrations were markedly elevated during active visceral leishmaniasis and showed a trend toward decline after treatment." (PMID 41471254, 2025). "Although derived from cutaneous disease, these findings support the biological plausibility that PTX3 may modulate host inflammatory responses in visceral leishmaniasis as well." (PMID 41471254, 2025).
vitamin D insufficiency (1 paper, 2022). "PTX-3 levels were significantly higher in patients with vitamin D insufficiency (20–29 ng/mL) than in the group with vitamin D sufficient (30–100 ng/mL)." (PMID 34544219, 2022).
tumor (166 papers, 2011 to 2026). "This study aimed to investigate the expression of inflammaging-related markers in RCC tissues, focusing on the role of PTX3, IL-6, and senescence-associated proteins in the tumor microenvironment." (PMID 41681886, 2026). "Increased PTX3 expression in tumor tissues has also been associated with poorer prognosis in individuals with HCC." (PMID 41462970, 2025). "Elevated PTX3 levels have been associated with tumor progression and aggressiveness, reflecting its dual role in cancer biology." (PMID 41515435, 2025). "CD68 expression was positive in ATC, indicating tumor-associated macrophage infiltration, but a few cells were double-positive for PTX3 and CD68." (PMID 41373493, 2025). "Our in vitro experiments and survey of publicly available PCa datasets exhibited that elevated expression of PTX3 in PCa was required for cell migration and associated with tumour metastasis." (PMID 39187920, 2024). "We identified a subset of tumor cells expressing Pan-Ck, Ck-7 and PTX3, associated with the only two patients in our cohort having distant metastasis at the time of the diagnosis and surgery." (PMID 39575252, 2024). "Several studies have demonstrated that PTX3 contributes to an anti-inflammatory phenotype in macrophages, suggesting a potential function of PTX3 in the crosstalk among tumor cells, tumor-associated stromal cells, and tumor-associated macrophages." (PMID 38243273, 2024). "High PTX3 expression levels in serum and tumor tissues have been associated with poor prognosis in various malignancies, suggesting its potential as a prognostic biomarker." (PMID 39594709, 2024). "A study investigating single nucleotide polymorphisms (SNPs) in the PTX3 gene revealed that different PTX3 genotypes were associated with variations in tumor stage and metastatic status." (PMID 39594709, 2024). "In studies examining various types of cancer, higher tumor grades were generally associated with elevated PTX3 expression." (PMID 39594709, 2024). "The results from the present study indicate that elevated plasma levels of PTX3 are associated with a more advanced Tumor, Node, Metastasis (TNM) stage in BC patients, and thus have potential as a biomarker for the prognostication of the disease." (PMID 38542446, 2024). "Both serum and tumor tissue expression of PTX3 protein were associated with similar prognostic outcomes, with no observed heterogeneity." (PMID 39594709, 2024). "In this study we show that, if compared to the other BC subtypes, high levels of PTX3 are mainly found in TNBC, where PTX3 transcript is predominantly expressed by tumor cells in respect to cells associated with tumor stroma/microenvironment." (PMID 37749607, 2023). "Different studies reported the role of PTX3 as an oncosuppressor acting through the modulation of tumor-associated inflammation and/or by blocking pro-tumor growth factors like various members of the FGF family." (PMID 37749607, 2023). "Conversely, low levels of PTX3 transcript are observed in tumor stroma/microenvironment associated cells, including endothelial cells (Endo), cancer-associated fibroblasts (CAF), macrophages, dendritic cells and lymphocytes (T and NK cells)." (PMID 37749607, 2023). "Infections, non-alcoholic fatty liver disease (NAFLD), and tumours are all associated with elevated pentraxin-3 (PTX3) levels." (PMID 37296126, 2023). "A subset of Mena-dependent genes, including PTX3, were also linked to immune modulation, another central process in tumour growth." (PMID 36959177, 2023). "Except for being a potent tumour suppressor, increasing evidence shows that an abundance of PTX3 is associated with either the grade of malignancy or a poor prognosis and contributes to acquired chemoresistance and cancer metastasis/invasion." (PMID 35090088, 2022). "Noteworthy, we found that PTX3 was associated with the tumor microenvironment (TME) and immune checkpoint inhibitors (ICIs), and we researched its regulation in immunotherapy." (PMID 36139597, 2022).
tumor (continued). "On the other hand, it has been demonstrated in PTX3 deficient mice that tumorigenesis is promoted and is mediated by complement-dependent tumor-promoting inflammation." (PMID 36362114, 2022). "In E0771‐Luc2 tumour‐bearing tamoxifen‐induced conditional Ptx3‐deficient mice, PTX3 expression was verified and attenuated PTX3 significantly reduced tumour growth and metastasis." (PMID 35090088, 2022). "It was further demonstrated that FGF2‐dependent angiogenesis, tumour growth and metastasis were enhanced in Ptx3‐deficient mice." (PMID 35090088, 2022). "Nevertheless, PTX-3 can be a valuable tool to assess as a risk factor for tumor occurrence in patients diagnosed with chronic hepatitis C virus infection." (PMID 36499628, 2022). "As a result of this anti-angiogenic activity, PTX3 overexpression causes a significant reduction of the tumor burden in both subcutaneously grafted and systemic MM models." (PMID 34066669, 2021). "In the context of several solid tumors, it has been demonstrated that the epigenetic repression of the Complement cascade regulator PTX3 in the tumor microenvironment is strictly linked to induction of complement-dependent tumor-promoting inflammation." (PMID 33922612, 2021). "Recently our group demonstrated in a 10-year retrospective cohort study that PTX3 expression was elevated in both neoplastic renal cell lines and tissues and strongly associated with complement system activation and tumor progression." (PMID 34572075, 2021). "Previous study proved PTX3 deficiency tumor manifested high macrophage infiltration, more cytokine production and high complement activation." (PMID 32984316, 2020). "PTX-3 is an inflammatory indicator often considered as a modulator of tumor-associated inflammation, with important roles in an array of cancers." (PMID 32587638, 2020). "In parallel with the inhibition of tumor-associated neovascularization, PTX3 overexpression resulted in a significant reduction in the recruitment of immune cell populations such as mast cells, macrophages, and T-lymphocytes." (PMID 31533326, 2019). "Genetic ablation of PTX3 results in a factor H-mediated increase of C3 complement component deposition, thus leading to a pro-tumor inflammatory context that confers increased susceptibility to mesenchymal and epithelial carcinogenesis." (PMID 31533326, 2019). "In these studies, chronic inflammation driven by the loss of PTX3 resulted in activation of the complement cascade which was critical for tumor formation." (PMID 31134065, 2019). "Overall, high PTX3 expression in tumor tissue from HCC was associated with lower survival after surgery." (PMID 31019517, 2019). "Accordingly, overexpression of PTX3 by tumor cells of different origin (including melanoma, prostate, and breast cancer cells) causes a significant inhibition of tumor-associated neovascularization and FGF-dependent tumor growth." (PMID 30349543, 2018). "PTX3 overexpression caused a significant delay of tumor growth in both murine and human tumor grafts." (PMID 30443492, 2018). "Global PTX3 deficiency was associated with more pronounced cancer-related inflammation and with a higher number of tumor-infiltrating macrophages." (PMID 28536575, 2017). "Immunohistochemical staining showed that increased PTX3 expression was significantly associated with tumor grade (P < 0.011) and differentiation (P < 0.019)." (PMID 27377307, 2016). "PTX3 may be linked to the gut microbiota or act as a component of the mucosal immune barrier, potentially influencing tumor regulation." (PMID 41479916, 2025). "Notably, the upregulation of several of these genes, particularly NCF1, HSPB1, PIGT, and PTX3, was associated with poor prognosis, supporting the idea that these genes play a pivotal role in tumor progression and patient survival." (PMID 40656950, 2025).
tumor (continued). "A key study establishing the protumorigenic role of complement comes from the demonstration of enhanced tumor initiation in Ptx3–/– mice where activation of the complement led to recruitment of tumor-associated macrophages, enhanced inflammation, ultimately promoting oncogenesis." (PMID 39964754, 2025). "Long pentraxin 3 (PTX3) is an inflammatory protein implicated in tumor progression." (PMID 41373493, 2025). "Moreover, we identified a specific subtype of tumor cells expressing PTX3, a molecule already associated with tumor progression in several types of cancer, in patients having distant metastasis at the time of the diagnosis." (PMID 40292277, 2025). "In several tumoral subtypes, via regulating complement-dependent and macrophage-associated tumor-promoting inflammation, it has been demonstrated that PTX3 may function as a promoter of cancer metastasis, invasion, and stemness." (PMID 38730589, 2024). "Moreover, our gene silencing experiments and survey of public datasets revealed that elevation of PTX3 levels in PCa was required for cell migration and associated with tumour metastasis." (PMID 39187920, 2024). "PTX3, a crucial component of innate immunity, serves as an extrinsic oncosuppressor by regulating Complement-mediated, macrophage-driven inflammation, influencing resistance against microbes, inflammation modulation, and tumor susceptibility." (PMID 38778378, 2024). "Patients with elevated PTX3 levels may represent a subgroup requiring early, more aggressive treatment strategies or additional diagnostic imaging to detect any potential tumour progression at an earlier stage." (PMID 38542446, 2024). "Besides, intracellular expression of ZNF148 and PTX3 increased obviously in tumor‐associated astrocytes (TAAs) at both transcriptional and protein levels, compared with NHAs." (PMID 37063077, 2023). "Some publications report that PTX3 may also act as an oncosuppressor by modulating tumor-associated inflammation or by blocking tumor growth factors such as different members of the FGF family." (PMID 36290747, 2022). "Meanwhile, PTX3 expression was associated with immune checkpoint genes, and immunotherapy potential biomarkers in multiple cancers, predicting special immunotherapy responses in different tumor types." (PMID 36139597, 2022). "Furthermore, the associations between PTX3 and tumor signaling pathway scores were examined in KIRC." (PMID 36139597, 2022). "In conclusion, PTX3 expression was associated with tumor survival and immunotherapy response, suggesting that PTX3 might serve as a biomarker and a reference for predicting the efficacy of immunotherapy." (PMID 36139597, 2022). "In COAD, the authors explained that the PTX3 gene was silenced by DNA methylation of the promoter and a putative enhancer, while increased PTX3 plasma levels reasonably reflected cancer-related inflammation associated with tumor growth." (PMID 36139597, 2022). "PTX3 has been known to have an essential role in tumor-associated inflammation." (PMID 34912809, 2021). "Pentraxin 3 has been proved its association with patients’ poor survival outcome in various tumor." (PMID 32984316, 2020). "Univariate analysis for the predefined variables showed that the pathological stage, presence of nodal and visceral metastases, Fuhrman grade, presence of necrosis, tumor size, and high levels of PTX3, were significantly associated with the risk of death and progression." (PMID 32345771, 2020). "In addition, as a consequence of PTX3 upregulation, in vivo grafting in immune-deficient mice resulted in reduced tumor burden/growth capacity of 5637-hPTX3 cells in comparison with 5637-Mock and wild-type cells." (PMID 31480336, 2019). "PTX3 overexpression caused a significant reduction of tumor angiogenesis/CD31+ areas." (PMID 31533326, 2019). "PTX3 deficiency triggers complement-dependent tumor-promoting inflammation." (PMID 31236125, 2019).